AHR (aryl hydrocarbon receptor)
Diseases named in the same sentence as AHR in open-access papers (continued):
Sharing a sentence is not in itself a finding about the gene and the disease.
tumor (continued). "Mechanistically, activation of the AhR in tumor-associated macrophages by tryptophan-derived bacterial indoles alters the cells polarization toward a protumor alternative antiinflammatory M2 phenotype and suppresses antitumor immunity." (PMID 38448800, 2024). "5-HTP subsequently activated AhR nuclear translocation, leading to a downregulation of cytokine and effector molecule and thereby causing T cells dysfunction in the tumor microenvironment." (PMID 39309474, 2024). "More significant nuclear localization of AHR and AHR associated activity was observed in the AMs of 4T1 tumor-bearing mice, compared to those from tumor-free mice." (PMID 39690159, 2024). "There is evidence that CAF is associated with tumor metabolism, and interestingly, AhR can be activated by small molecules produced in metabolism." (PMID 38434684, 2024). "For instance, in pancreatic ductal adenocarcinoma, tumor-associated macrophages (TAMs) with high AhR activity, driven by Lactobacillus-mediated metabolization of dietary tryptophan to indoles, support tumor growth and suppress anti-tumor immunity." (PMID 39438986, 2024). "IL4I1 is upregulated in multiple tumor types, associated with poor prognosis, and is more closely associated with AhR activation than IDO expression." (PMID 38339226, 2024). "Recent discoveries suggest that indole metabolites produced by Lactobacillus induce immunosuppression by activating the AHR on tumor-associated macrophages, thereby fostering tumor growth." (PMID 39351241, 2024). "Specifically, the activation of the MAPK pathway by AhR can lead to increased AR signaling, while cross-talk with the Wnt pathway can influence gene expression profiles associated with tumor growth and metastasis." (PMID 39184676, 2024). "No clear relationship between the tumor-associated macrophages (TAM) infiltration level in the tumor nest and AhR expression was observed in cancer cells." (PMID 38680496, 2024). "Previous studies have also found that the binding of tumor cells AhR to ligands can cause activation of the PD-L1 pathway." (PMID 38887597, 2024). "This exposure, when combined with genetic polymorphisms in the AHR gene, exacerbates tumor progression and increases the risk of developing CRPC." (PMID 39600743, 2024). "AHR sustained activity is observed in various tumor types and is often associated with unfavorable prognosis." (PMID 39204085, 2024). "Macrophages found within the TME are known as tumor-associated macrophages (TAMs), and their polarization state and functionality are similarly influenced by AhR activation, leading to enhanced immunosuppression." (PMID 38339226, 2024). "Hezaveh and colleagues showed that indole-mediated activation of AhR signaling in tumor-associated macrophages (TAMs) suppress anti-tumor immunity." (PMID 39713022, 2024). "In vivo experiments in mice have demonstrated that ovarian tumoral IDO1 mediates PD-1 upregulation on CD8+ T cells via AhR and causes infiltration of suppressive immune cells in the tumor microenvironment, augmenting ovarian tumor growth." (PMID 38807762, 2024). "The bacterial tryptophan metabolites, indoles, activate the aryl hydrocarbon receptor (AHR) in tumor-associated macrophages, promoting their immune-suppressive M2 polarization." (PMID 39409962, 2024). "The mechanism behind AHR-deficiency in impeding migration of NK cells to tumours was deciphered through a AHR−/− knockout cell-line." (PMID 38958472, 2024). "Tryptophan metabolites generated by Lactobacillus can activate the aryl hydrocarbon receptor (AhR) in tumor-associated macrophages." (PMID 39420203, 2024). "Along with the indole pathway, indole production activates the aryl hydrocarbon receptor (AhR) in tumor-associated macrophages (TAMs), and thus inhibits intratumoral CD8+ T cell function." (PMID 38218942, 2024).
tumor (continued). "Activation of AhR by tryptophan catabolites is associated with migration and proliferation of cancer cells, whereas knockdown of AhR is associated with an increase in tumor-infiltrating lymphocytes and tumor regression." (PMID 38632994, 2024). "Tryptophan-derived microbial metabolites activate the aryl hydrocarbon receptor in tumor-associated macrophages to suppress anti-tumor immunity." (PMID 36899929, 2023). "AHR has been identified as a tumor-associated protein and therapeutic target molecule in recent years." (PMID 37179416, 2023). "Nearly all tumors express elevated levels of at least one of the Trp-degrading enzymes and depending on the tumor type AHR activation associates with the expression of one or more of these enzymes." (PMID 37696456, 2023). "The relationship between SOCS3 and the AhR was further investigated in AhR deficient mice in the AOM/DSS tumor model where SOCS3 levels were increased in tumors compared to uninvolved mucosa." (PMID 38651159, 2023). "Loss of intestinal AhR increased organoid-forming efficiency of stem and progenitor cells, enhanced organoid size and number, increased tumor size and the number of tumors in the distal colon per mouse and cecum weight." (PMID 38651159, 2023). "Our previous research also found that AhR independently activates downstream target genes 16, AhR pathway activation has been associated with stem-like peculiarities and radiation resistance in tumor cells 17 and can be stabilized by de-ubiquitination." (PMID 37056388, 2023). "For instance, there is a need to explore how AhR knockdown or pharmacological inhibition would affect PM2.5 induced tumor promotion in lung AT2 cells with EGFR driver mutations and to compare the impact of PM2.5 with high or low PAH content on these responses." (PMID 37696458, 2023). "High expression of AHR drives the expression of CD39 in tumor-associated macrophages promoting CD8+ T-cell dysfunction." (PMID 37189838, 2023). "ASB2-deficiency phenocopied AhR-deficiency in natural killer cells in terms of the capability of natural killer cells to invade and infiltrate tumor tissues." (PMID 37830596, 2023). "Recently, ligand-mediated modulation of AhR signaling pathways and the associated tumor microenvironment is emerging as a potential approach for developing cancer immunotherapeutic drugs." (PMID 37241719, 2023). "IL4I1 shows enhanced expression in a wide variety of tumor types, and its Trp-metabolizing activity yields various downstream metabolites which are associated with AhR agonism, including I3LA, I3AA, I3A and KynA." (PMID 36765849, 2023). "Kynurenine (KYN) generated in the tumor microenvironment induces AHR activation, which is related to glioma-associated immunosuppression." (PMID 37179416, 2023). "A recent study has shown that high level of IL-2 induces the conversion of tryptophan to 5-hydroxytryptophan (5-HTP), and 5-HTP activates AhR, thereby causing T cells dysfunctional in the tumor microenvironment." (PMID 36966295, 2023). "The immunosuppressive effects mediated by IDO-Kyn-AHR depend on the interaction of Treg and tumor-associated macrophages (TAMs)." (PMID 37936703, 2023). "As an excretory organ, the kidneys are highly exposed to carcinogens and AHR has been found to be up-regulated in ccRCC tumours, in which it is associated with pathological tumour stage, histological grade, and poor prognosis." (PMID 36725335, 2023). "AhR deficiency drastically impaired the infiltration of lymphocytes into the tumor microenvironment." (PMID 37830596, 2023).
tumor (continued). "Other studies have shown that the pro-tumor and pro-metastatic activity observed in melanoma cells upon AHR absence is associated with the activation of the pluripotency inducer SOX2 and the aldehyde dehydrogenase enzyme IAI (ALDH1A1)." (PMID 35465323, 2022). "We propose that AhR functions as a “molecular bridge”, linking disproportionate toxin exposure and policies which underlie environmental injustice with tumor cell behaviors which drive poor patient outcomes." (PMID 36588678, 2022). "The AhR is a cell cycle mediator that has been associated with several functions in cell proliferation and differentiation, gene regulation, tumor development, and metastasis." (PMID 35678668, 2022). "Accumulating evidence has shown that AHR expression is upregulated in most tumor cells and is closely associated with tumor proliferation, invasion, metastasis, and immune escape." (PMID 36266304, 2022). "AhR has been implicated in cancer stemness and immune evasion in various tumor types serving as a “molecular bridge” between environmental exposure and poor patient prognosis." (PMID 36588678, 2022). "The AhR is intimately associated with the induction of Treg and PD-1 upregulation, indicating tumor-derived kynurenine and gut tryptophan metabolites in the co-ordination of Treg and CD8+ t cell exhaustion." (PMID 36613754, 2022). "It is well-established the activation of AhR in immune cells hinders efficient antitumor immunity via stimulation of antigen-presenting DCs, tumor-associated macrophages (TAMs), immunosuppressive Tregs and modulation of effector CD8 and CD4 T-cell functions." (PMID 35173722, 2022). "Specific clinical focus has increasingly centered on the metabolic mechanisms of tumor-associated immunosuppression exerted by the tryptophan-kynurenine-aryl hydrocarbon receptor (Trp-Kyn-AhR) pathway in the TME." (PMID 35173722, 2022). "Associations between favorable tumor characteristics and AhR levels seen in the present study have previously been reported in some but not all studies." (PMID 34094928, 2021). "AhR activated by 5-HTP directly induced tumor-specific CD8+ TILs cell exhaustion in vivo, causing a coordinated upregulation of inhibitory receptors, such as PD-1, LAG-3, CD39 and downregulation of cytokines, thereby causing dysfunctional T cells in the TME." (PMID 33924971, 2021). "Overexpression of AhR in HCC has been shown to be associated with its tumour proliferation and invasion." (PMID 34680327, 2021). "In a previous study, we observed that AHR-deficiency was associated with low infiltration of lymphocytes into the tumor microenvironment." (PMID 33717133, 2021). "AhR has been widely analysed and seems to be associated with tumour genesis and different disease progression phases." (PMID 34640369, 2021). "Accordingly, a recent study has shown that kynurenine controls tumor associated macrophage (TAM) activation via AhR signaling, leading to CD39 expression in TAMs and impairing the T cell response to glioblastoma tumor cells." (PMID 33924971, 2021). "The IDO-Kyn-AhR signaling pathway has been shown to mediate immunosuppression involving Tregs and tumor-associated macrophages, which can be reversed by AhR inhibition." (PMID 33763068, 2021). "The differentiation of IL-10 producing Tr1 cells can be promoted by AHR contribute to tumor-associated immunosuppression together with Foxp3+ Tregs." (PMID 34659216, 2021). "In this study, the AhR expression landscape of 33 different cancers was presented and the underlying effects of AhR on the tumor immune microenvironment were investigated." (PMID 34290693, 2021). "We showed that tumours presenting a high AhR activity were in fact associated with a high expression of AHR mRNA." (PMID 32988402, 2020). "We demonstrate that IDO-Kyn-AHR-mediated immunosuppression depends on an interplay between Tregs and tumor-associated macrophages, which can be reversed by AHR inhibition." (PMID 32782249, 2020).
tumor (continued). "The kynurenine-AhR metabolic circuit has been implicated in the dormancy of stem-like tumor repopulating cells (TRC) in response to IFN-γ stimulation." (PMID 32483452, 2020). "It was predicted to be damaging by multiple in silico tools and AHR tumour immunohistochemistry demonstrated loss of the normal nuclear staining pattern, suggestive of an inactivating mutation." (PMID 31996203, 2020). "These risk factors modulate the profiles of tumor-infiltrating leukocytes (TILs), at least in part, through aryl hydrocarbon receptor (AhR)-dependent signal pathways." (PMID 32707850, 2020). "They further showed that AhR loss of function sensitized tumor cells to Erlotinib, an EGFR inhibitor, suggesting a promising combinatorial antitumor strategy for the treatment of TNBC." (PMID 33015128, 2020). "Tumor progression rate of B16IDO tumors was delayed in AHR deficient mice (AHRKO) and depletion of macrophages with αCSF1-R or clodronate liposomes delayed the progression of IDO-expressing tumors but not wild-type tumors." (PMID 32782249, 2020). "The beneficial effect of Api on tumor progression was mediated by inhibiting the transcriptional activity of AhR to regulate the expression of genes associated with BRAFi-resistance." (PMID 32708687, 2020). "We further characterised AHR Q383H as an activating driver mutation associated with high AhR activity in luminal tumours." (PMID 32988402, 2020). "Loss of the normal nuclear pattern of AHR tumour staining suggests that it is a loss-of-function variant causing failure of nuclear translocation." (PMID 31996203, 2020). "The DBP and BBP caused tumor formation in breast by stimulating aryl hydrocarbon receptor (AhR); thus, activating the downstream cyclic AMP/PKA, CREB1, and HDAC6 signaling pathway." (PMID 32764471, 2020). "These include the aryl hydrocarbon receptor (AHR), the progesterone receptor (PR), and, with particular relevance to macrophage‐rich tumor microenvironments, tumor‐associated macrophages (TAMs)." (PMID 32918364, 2020). "The autocrine binding of kynurenine to the aryl hydrocarbon receptor in cancer cells causes the transcriptional activation of genes related to tumor invasiveness." (PMID 30200472, 2018). "Increased expression of the AhR is associated with deregulation of cell–cell contact and tumor malignancy." (PMID 29487603, 2018). "This is also true with altered glial cells: indeed, several studies have recently underlined the role of the AhR in tumor cell proliferation in the nervous system." (PMID 30149528, 2018). "AHR activation increases the survival of tumor cells, whereas AHR activation causes tolerance in immune cells." (PMID 29301348, 2018). "The aryl hydrocarbon receptor (AHR) is present in the cytoplasm as part of a chaperone complex and has been implicated in tumour promotion and progression." (PMID 28298557, 2017). "AHR was also found to be under-expressed in invasive adenomas and those tumours with demonstrated AIP mutations." (PMID 28649092, 2017). "In contact-inhibited liver progenitor cells, the AhR agonists induce a range of effects potentially linked with tumor promotion." (PMID 27274734, 2016). "Overly consumption or deprivation of tryptophan represents the key features of tumour microenvironment, and consequent accumulation of the low-affinity AhR agonist Kyn is associated with tumour progression." (PMID 26059097, 2015). "AHR is a ligand activated transcription factor whose activity is linked with alterations in cell proliferation, apoptosis, adipose differentiation, tumor promotion, immune function, vitamin A status, development and reproductive functions." (PMID 26627005, 2015). "Other evidence demonstrates that knockdown AhR activity causes tumor burden changes and inhibits tumor growth within 2-4 weeks." (PMID 25226618, 2014).
tumor (continued). "This is of particular relevance since the human aryl hydrocarbon receptor is implicated in various processes such as transformation, tumor genesis, and inflammation." (PMID 24898306, 2014). "Several epidemiological studies have shown that TCDD promotes cancer, and experiments in AHR-deficient mice have shown that AHR is essential for the tumor-promoting effects of TCDD." (PMID 23420531, 2013). "It is noteworthy that centrosome aberrations and multipolar mitoses are frequent findings in pre-cancerous lesions of the mammary gland and the prostate, both tumor entities in which aberrant AhR expression has been suggested to play a pathogenic role." (PMID 20565777, 2010). "Ligand-independent AhR up-regulation has been documented in tumours and linked with promotion of cell proliferation." (PMID 19340314, 2009). "In contrast, in oncology, AHR-mediated immunosuppression may cause tumor progression and metastasis." (PMID 41540003, 2026). "Likewise, tumor-associated metabolites such as kynurenine, lactate, and adenosine maintain Treg function through activation of AhR and HIF-1α signaling." (PMID 41394821, 2025). "The AhR signaling pathway has been implicated in a variety of cellular processes that play a significant role in tumor pathogenesis, including the regulation of cell proliferation, cell cycle control, the modulation of adhesion, and the regulation of cell migration." (PMID 40149846, 2025). "Therefore we performed RNA-seq analysis of tumor-infiltrating AhR-sufficient or AhR-deficient ‘progenitor exhausted’ CD8 T cells, 24 h after anti-PD1 treatment." (PMID 41331250, 2025). "Altering the composition of the intestinal flora, increasing the abundance of beneficial intestinal bacteria, decreasing tryptophan metabolites, decreasing inflammation inhibiting the expression of AhR and M2-type tumor-associated macrophages, and enhancing anti-tumor immunity." (PMID 40066456, 2025). "It builds on earlier findings that certain Lactobacillus strains may impact tumor-associated macrophages via the AhR pathway." (PMID 41471890, 2025). "In PDAC, high AhR activity was associated with TAMs pro-tumor activity." (PMID 40361394, 2025). "Additionally, the context-dependent effects of AhR require further investigation to fully understand the mechanisms underlying its bidirectional influence on tumor progression." (PMID 39184676, 2024). "AhR signaling and overexpression has originally been associated with several tumor types." (PMID 39472005, 2024). "Additionally, approximately 5,000 genes regulated by AhR are highly relevant to epigenetic alterations and the differentiation associated with tumor heterogeneity." (PMID 38680496, 2024). "Moreover, the association of AhR activity with increased tumor aggression and worse oncologic outcomes has been reported." (PMID 39339278, 2024). "However, blockade of the AhR signaling pathway requires careful consideration, as AhR agonism can be associated with anti-tumor effects in certain contexts." (PMID 38339226, 2024). "Given that Kyn-AHR axis has been shown to be associated with of many kinds of tumor immunosuppression, how to overcome or improve relational therapeutic deficiencies is a challenge for the tumor therapy." (PMID 38755645, 2024). "Moreover, it is worth noting that indoles signal through the AhR in tumor-associated macrophages but reduce the efficacy of immunotherapy in pancreatic cancer." (PMID 39409962, 2024). "AhR activation has been implicated in cellular proliferation in a variety of tumor types." (PMID 38339226, 2024). "The strategic activation of the AHR through a selective AHR modulator (SAhRM) may offer effective anti-tumour therapy in VHL-mutated ccRCC, reducing the need for surgical interventions." (PMID 39336758, 2024). "This series of studies suggests that benzopyrene and tumor cell AhR in tobacco cause elevated PD-L1 levels, which may be another potential mechanism for smoking to increase tumor immune escape." (PMID 38887597, 2024).